CSF1R (colony stimulating factor 1 receptor)
Diseases named in the same sentence as CSF1R in open-access papers (continued):
Sharing a sentence is not in itself a finding about the gene and the disease.
tumor (1,262 papers, 2007 to 2026). "Targeting tumor-associated macrophages/microglia via colony-stimulating factor 1 receptor (CSF-1R) inhibition is potentially effective in suppressing GBM recurrence." (PMID 41365876, 2025). "The selective CSF‐1R inhibitor vimseltinib blocks CSF‐1R signaling, reducing M2‐like tumor‐associated macrophages." (PMID 40717900, 2025). "The study also indicated the presence of tumor macrophages (CD68+CD163+CSF1R+SIGLEC5+) associated with immunotherapy resistance." (PMID 40404633, 2025). "Colony-stimulating factor 1 receptor (CSF1R) is a promising imaging biomarker for neuroinflammation or tumor-associated macrophages." (PMID 40166008, 2025). "CSF‐1R inhibition significantly reduces F4/80+ tumor‐associated macrophage while increasing the ratio of CD8+/CD4+ T cells." (PMID 40717900, 2025). "Its unique targeting profile, particularly the inhibition of CSF-1R which regulates tumor-associated macrophages, provides potential advantages in the NET treatment landscape." (PMID 40392078, 2025). "To this end, we selected the PLX3397 drug (also known as pexidartinib), which is widely used for the blockade of microglia and tumor-associated macrophages through the inhibition of the colony stimulating factor 1 receptor (CSF1R)." (PMID 40578365, 2025). "Targeting CSF1R appears to be a promising anti-tumor strategy and the presence of CSF1R-positive macrophages is associated with poor survival." (PMID 39425000, 2025). "CSF1R inhibitors are recommended if the tumor is “unresectable” or if surgery would be associated with significant morbidity." (PMID 40392406, 2025). "Their research showed that surufatinib not only inhibits angiogenesis but also modulates the immune microenvironment by affecting tumor-associated macrophages through CSF-1R inhibition." (PMID 40392078, 2025). "Colony-stimulating factor 1 receptor (CSF1R) is a promising imaging biomarker for neuroinflammation and tumor-associated macrophages." (PMID 40360942, 2025). "Tumour-associated macrophages, which play an important role in the tumour microenvironment, can be reprogrammed from an immunosuppressive M2 phenotype to an immunostimulatory M1 one by downregulation of the CSF-1R signalling pathway, using siRNA." (PMID 40871103, 2025). "IF staining confirmed a decrease of BrdU+ tumor cells, loss of CSF-1R signal and infiltration of CD20+ B and CD8+ T cells following the double combination in lung metastases." (PMID 40568104, 2025). "For example, high baseline expression of CSF1R or its ligands (CSF1, IL-34) in the tumor microenvironment has been associated with better responses to CSF1R inhibitors." (PMID 40821795, 2025). "While CSF1R inhibition initially suppresses tumor progression, prolonged treatment has been linked to adaptive resistance in tumor cells." (PMID 40800581, 2025). "Mechanistically, IL34 increases migration of monocyte-derived tumor-associated macrophages (MD-TAMs) in primary tumors and lung metastases through colony-stimulating factor 1 receptor (CSF1R)." (PMID 40538439, 2025). "CSF1R antagonists were originally developed to deplete tumor-associated macrophages, which promote tumor growth, survival, angiogenesis, treatment resistance, and metastasis." (PMID 38643194, 2024). "For example, using C–C chemokine 2 (CCL2) to block the recruitment of tumor-associated macrophages/microglia, or the colony-stimulating factor-1 (CSF-1R) inhibitor to impair the survival of macrophages/microglia." (PMID 38238749, 2024). "CSF-1R can induce the proliferation, survival, and differentiation of tumor-associated macrophages, which are abundant in various tumor-microenvironment activities, thereby promoting tumor immune evasion and drug resistance." (PMID 38172256, 2024). "As highlighted in this review, CSF-1R expression in tumor cells is indeed associated with increased proliferation, expression of EMT markers, development of invasive capabilities, drug resistance and acquisition of stem-like features." (PMID 38254773, 2024).
tumor (continued). "IL-33 combined with anti-CSF1R or p38 inhibitor to regulate tumor-associated macrophages (TAMs) had a synergistic antitumor effect." (PMID 38238529, 2024). "This compensatory effect and accelerated tumor growth in response to prolonged CSF-1R inhibition have recently been linked to an augmented recruitment of granulocytes into the tumor microenvironment (TME)." (PMID 39409110, 2024). "Given that CSF-1R is closely associated with M2 macrophage polarization, the importance of M2 macrophages in tumor promotion has been emphasized." (PMID 39678502, 2024). "Intratumoral CSF-1/CSF-1R signaling has been reported to play a key role in triggering the recruitment of tumor-associated macrophages leading to tumor growth and facilitating metastasis." (PMID 39186767, 2024). "CSF1R is unique compared to traditional SMKI targets as it primarily resides on tumor-associated macrophages (TAMs) within the tumor immune microenvironment." (PMID 38791529, 2024). "Colony stimulating factor 1 (CSF1) signaling through its receptor, CSF1R, plays a pivotal role in the proliferation and differentiation of myeloid-derived suppressor cells (MDSCs) and M2-type tumor-associating macrophages (M2-TAMs)." (PMID 39201328, 2024). "Targeting CSF-1R can reduce GB-associated macrophages in the tumor microenvironment and promote GB-associated macrophage repolarization, limiting tumor development, avoiding the recurrence of glioblastoma and promoting cytotoxic T-cell activation." (PMID 38523646, 2024). "For example, interruption of CSF‐1R can cause the accumulation of monocyte‐derived macrophages leading to tumor recurrence." (PMID 39429877, 2024). "CSF1R+PDCD1+ tumour‐associated macrophages (TAMs) exhibit strong signal communication with MAIT cells at the tumour edge." (PMID 39350478, 2024). "CSF-1R+ macrophages are related to immunosuppression and tumor progression, and the expression of CSF-1R in TAMs is associated with an unfavorable prognosis and resistance to tumor immunotherapy." (PMID 38983267, 2024). "Downregulation of colony-stimulating factor-1 receptor (CSF-1R) can reprogram immunosuppressive M2 tumor-associated macrophages into pro-inflammatory anticancer phenotype M1." (PMID 39273469, 2024). "Activation of CSF1R also enhances recruitment of tumor-associated macrophages (TAMs) to the tumor site, hence the poor prognosis was observed." (PMID 38822100, 2024). "PID has been used for HER2 detection in BC, Colony Stimulating Factor 1 Receptor (CSF1R) detection in tumor-associated macrophages, quantitative detection of Estrogen receptor alpha (ERα), and intratumoral pharmacokinetics of new HER2-targeted ADC." (PMID 38748758, 2024). "This process was demonstrated by an elevated expression of CSF1R from the tumor invasion edge to distant metastasis being associated with CpG-methylation of the miR-34a promoter in the primary CRC." (PMID 38725047, 2024). "The administration of PLX3397 (pexidanib), an antagonist of CSF-1R, caused the depletion of TAMs and delayed tumor regeneration after radiotherapy." (PMID 37542283, 2023). "To determine the impact of Regorafenib on tumor-associated macrophages in vivo, we evaluated the murine macrophage marker F4/80 as well as CSF1R expression in the pancreata of Regorafenib- and PEG-treated mice by immunohistochemistry." (PMID 37620408, 2023). "Regorafenib transforms tumor-associated macrophage from M2 type to M1 type with anti-tumor function by inhibiting the colony-stimulating factor 1 receptor." (PMID 37404825, 2023). "Regorafenib was previously shown to reduce tumor-associated macrophages and potently inhibit colony-stimulating factor 1 receptor (CSF1R), also known as CD115, in biochemical assays." (PMID 37013652, 2023). "Colony-stimulating factor-1 (CSF1), also known as macrophage colony-stimulating factor, acts as a key cytokine in the production, recruitment, and activation of tumor-associated macrophages (TAMs) by binding with CSF1 receptor tyrosine kinase (CSF1R)." (PMID 37097499, 2023).
tumor (continued). "Of note, the use of GM-CSF and TAM (tumor associated macrophages) inhibitors, like CSF-1R, have shown promising results in blocking the crosstalk between macrophages and tumor cells." (PMID 37305676, 2023). "This anti-tumor effect is induced by an increase in anti-tumor macrophages caused by reduction of a well-known pro-tumor macrophage promoter, CSF1R." (PMID 38100351, 2023). "Analysis of the tumor microenvironment demonstrated greater CD8 T cell infiltration and a reduction in tumor-associated macrophages following CSF1R inhibition in both tumor models." (PMID 37505292, 2023). "Specific gene translocations, which led to the recruitment of CSF-1R-expressing cells such as monocytes, macrophages, and some tumor cells, were the primary cause of TSGCT." (PMID 37923984, 2023). "CSF1R is also expressed by other tumor-associated myeloid cells including neutrophils, dendritic cells, and myeloid-derived suppressor cells (MDSCs)." (PMID 37266435, 2023). "Several drugs against CSF1R have shown promising antitumor efficacies by inhibiting the survival of M-MDSCs and tumor associated macrophages (TAMs) and are being tested in in cancer patients." (PMID 36739406, 2023). "Studies indicated that CSF-1R is mainly expressed in tumor cells, while CSF-1R has also been reportedly expressed in tumor-associated macrophages (TAMs) and involved in tumor immune escape." (PMID 38067341, 2023). "To address potential non-tumor cell autonomous effects of Regorafenib, we also examined its impact on tumor-associated macrophages, in particular since CSF1R has been reported as target of Regorafenib." (PMID 37620408, 2023). "In mouse models, inhibiting CCR2 and CSF-1R can antagonize the ability of tumor-associated macrophages to suppress T cell responses." (PMID 36143975, 2022). "Here, Mir34a inactivation resulted in a Csf1r-dependent increase in tumor-associated fibroblasts, macrophages, neutrophils, T- and B-cells." (PMID 36147476, 2022). "Multiple colony stimulating factor receptor 1 (CSF-1R) inhibitors are currently in clinical trials for their ability to polarize tumor associated macrophages to anti-tumorigenic M1 phenotype." (PMID 35638450, 2022). "In a Lewis lung carcinoma (LLC) mouse model, CSF-1/CSF-1R blockade was found to deplete intra-tumoural NK cells and increase tumour metastasis, due to a loss of the TAM-derived NK survival factor IL-15." (PMID 35020853, 2022). "In primary CRCs elevated expression of CSF1R was detected at the tumor invasion front and was associated with CpG methylation of the miR-34a promoter as well as distant metastasis." (PMID 36147476, 2022). "CD115, also known as colony-stimulating factor 1 receptor (CSF1R), is a surface receptor expressed on tumor-associated macrophages." (PMID 35406584, 2022). "CSF-1R inhibitors inhibit immunosuppressive tumor-associated macrophages; ongoing clinical trials are testing CSF-1R inhibitors as a monotherapy or combination therapy." (PMID 35806328, 2022). "CSF-1R, a tyrosine kinase transmembrane receptor on M2 macrophages, is currently the most studied tumor-associated macrophages (TAMs)." (PMID 36338975, 2022). "Colony stimulating factor 1 receptor (CSF1R) mediates tumorigenesis in the TME by enhancing tumor associated macrophage (TAM) and myeloid-derived suppressor cell (MDSC) infiltration, facilitating immune escape." (PMID 36230744, 2022). "Co-encapsulation of CSF-1R siRNA and M2pep can target M2 tumor-associated macrophages for reprogramming to the M1 type, resulting in increased anti-tumor immune responses." (PMID 36364057, 2022). "CSF-1R act as cell-surface receptors for the cytokines CSF-1 and IL-34 that are secreted by tumor cells and can cause the recruitment of M2-macrophages to support tumorigenesis." (PMID 35455743, 2022). "Our results imply that Csf1r critically contributes to tumor formation caused by loss of Apc in intestinal epithelial cells." (PMID 36147476, 2022).
tumor (continued). "Emerging data indicated that intratumor CSF-1/CSF-1R signaling can cause the recruitment of TAMs and the development of pro-tumor inflammatory environment, thereby leading to tumor growth and metastasis." (PMID 35444953, 2022). "CSF1R is expressed by cancer-associated fibroblasts (CAFs) and mediates their tumor-promoting phenotype." (PMID 35315360, 2022). "When CSF-1/CSF-1R is activated, tumor-associated macrophages (TAMs) secrete growth factors that contribute to tumor growth or metastasis, leading to a higher rate of recurrence." (PMID 35000616, 2022). "Some studies have confirmed that CSF1R + macrophages are associated with poor survival of various tumor types, so therapies targeting CSF1R-related signal transduction pathways such as CSF1R inhibitors have been proven effective against cancer." (PMID 35812745, 2022). "Reversely, the depletion of Treg cells using phosphoinositide 3-kinase δ (PIK3δ) inhibitors resulted in a significant increase in CSF1R+ tumor-associated macrophages (TAM), which again led to the suppression of CD8+ T cell function." (PMID 36230505, 2022). "Although multiple experimental mAbs have shown evidence of target specificity, characterised by increased serum CSF-1 and reductions in M2-associated CD163+, CD206+, and CSF-1R+ TAMs, insufficient anti-tumour activity has been displayed." (PMID 35020853, 2022). "Anti-GR1 antibody depletes both Ly6G+ granulocytes and Ly6Chi monocytes simultaneously, while anti-CSF1R antibody depletes resident subset of monocytes and tissue- and tumor-associated macrophages together." (PMID 34496935, 2021). "We performed an exploratory analysis to examine the relationship of carcinoma cells expressing CSF-1R in the context of tumor-associated macrophages stratified by ER expression." (PMID 34830923, 2021). "Kumar and coworkers employed CSF1R inhibition to disrupt chemokine secretion by cancer associated fibroblasts (CAF) abolishing recruitment of pro-tumor granulocytic myeloid-derived suppressor cells (MDSCs)." (PMID 33842370, 2021). "CSF-1R+ carcinoma cells are significantly associated with stromal tumor-infiltrating lymphocytes; intraepithelial lymphocytic infiltrates expressing CD8, FOXP3, TIM3, LAG3, and PD-1; and PD-L1+ carcinoma cells (p < 0.001)." (PMID 34830923, 2021). "Inhibition of the CSF-1/CSF-1R signaling axis has been the most thoroughly investigated mechanism to deplete tumor-associated macrophage populations." (PMID 33924237, 2021). "Secondly, we did not evaluate the immunohistochemical expression of CSF-1, a major ligand of CSF-1R that influences the recruitment and polarization of M2 tumor-associated macrophages." (PMID 34830923, 2021). "The administration of additional doses of ODN1826 caused delayed tumor growth or complete tumor regression in some mice in comparison to those treated with three doses, and this effect was similar to that caused by anti-CSF-1R therapy." (PMID 34205330, 2021). "The goal of CSF-1/CSF-1R blockade is to reduce accumulation of immunosuppressive tumor-associated macrophages and MDSCs in the tumor microenvironment." (PMID 33537102, 2021). "It was found that by administering PLX-3397, a CSF-1R antagonist that can cross the blood brain barrier, the number of tumor-associated microglia was drastically reduced." (PMID 34843542, 2021). "Blocking monocyte recruitment and the subsequent activation of tumor-associated macrophages (TAMs) via inhibition of CSF-1/CSF-1R is a novel immunotherapeutic strategy 94,95." (PMID 34158855, 2021). "Of note, despite their capacity to eliminate tumor-associated macrophages, limited anti-cancer activity has been observed with use of CSF-1R inhibitors alone or in combination with chemotherapeutic agents." (PMID 34830923, 2021). "Colony stimulating factor 1 receptor (CSF1R) expression has a key role allowing the switching of M1 macrophages into M2 tumor-associated macrophages." (PMID 34885091, 2021).
tumor (continued). "Tumor-associated M2 polarized macrophages (TAMs) promote tumor cell to bone metastasis through CCL2/CCR2 or colony-stimulating factor 1 (CSF1)/CSF1R signaling." (PMID 34831167, 2021). "Lower CSF-1R expression, less tumor-associated macrophages, and less M2-like macrophages in tumors with CSF1R genotype A_G also provide an explanation why patients with this germline variant had better clinical outcome." (PMID 34830445, 2021). "Firstly, our study was designed to evaluate the expression of CSF-1R on carcinoma cells and tumor-associated macrophages using a single biomarker immunohistochemistry." (PMID 34830923, 2021). "In some studies, inhibition of CSF1R depleted tumor-associated macrophages but unexpectedly promoted metastasis in 4T1 orthotopic syngeneic models." (PMID 33953710, 2021). "Preclinical studies have shown that targeting CSF-1/CSF-1R signaling depletes tumor-associated macrophages by inducing apoptotic death, inhibits their recruitment from circulating monocytes, and induces M2–M1 polarization." (PMID 34830923, 2021). "Tumor-associated macrophages (TAMs) represent another early innate immune cell with key roles in tumor development, recruited by chemokines released by tumor cells and associated stroma in a colony-stimulating factor 1 (CSF-1)-CSF-1R-dependent manner." (PMID 34685652, 2021). "Taking this and our prior study together, we find that germline CSF1R c.1085A>G variant had a great impact on macrophage functions, tumor immune microenvironment, and clinical outcome." (PMID 34830445, 2021). "All subsets expressed high levels of Cd11b, Csf1r, Csf2ra, Cd14, Cd64 and Cd68 confirming their initial classification as tumor-associated macrophages and monocytes." (PMID 34381732, 2021). "Both wild type and CSF1R knockout mice received different treatments that target tumor cells or tumor-associated cells." (PMID 33544755, 2021). "Recent studies in humans and mice that focussed on targeting tumor-associated macrophage infiltration via blockade of colony stimulating factor-1 receptor (CSF-1R) have shown promise." (PMID 33441138, 2021). "A recent preclinical study showed that targeting tumor associated macrophages (TAMs) using a colony stimulating factor 1 receptor (CSF-1R) combined with radiation results in increased survival of mice." (PMID 35096619, 2021). "The results showed CRCs harboring CSF1R c.1085 A>G variant had higher CD40LG and IL-2 expression in tumor tissues than those with CSF1R c.1085 genotype A_A." (PMID 34830445, 2021). "A recent study has demonstrated that in primary colorectal cancer, the elevated expression of receptor tyrosine kinase CSF1R at the tumor invasion was associated with poor patient survival and a mesenchymal-like subtype 24." (PMID 34729112, 2021). "It is also well established that CSF-1R and tumor-associated macrophage (TAM) expression correlate with poorer patient outcomes across various cancers, including malignant gliomas." (PMID 33027976, 2020). "Recently, it was proven that the overexpression of the natural ligands of CSF1R (CSF1 or IL-34) is associated with tumour progression and poor survival in lung cancer patients." (PMID 31809612, 2020). "Previous epigenetics studies have revealed an association between CSF1R methylation and tumor proliferation or migration." (PMID 32724427, 2020). "Several patients experienced clinical benefit with tumor mutations in cKIT, CSF-1R, PDGFRα, PDGFRβ, VEGFR1, VEGFR2, FLT3, FGFR2, RET, and TrkA." (PMID 32292573, 2020). "Colony stimulating factor 1 receptor (CSF1R) expression allows the switching of type 1 macrophages into type 2 tumor-associated macrophages." (PMID 35582435, 2020). "The following tumor mutations were reported in patients with clinical benefit: cKIT (n = 1), CSF-1R (n = 1), PDGFRα (n = 2), PDGFRβ (n = 1), VEGFR1 (n = 1), VEGFR2 (n = 2), FLT3 (n = 1), FGFR2 (n = 2), RET (n = 1), and TrkA (n = 1)." (PMID 32292573, 2020).